STAT3 (signal transducer and activator of transcription 3)
Diseases named in the same sentence as STAT3 in open-access papers (continued):
Sharing a sentence is not in itself a finding about the gene and the disease.
diabetic nephropathy (continued). "Blocking IL-6/STAT3 signaling defers inflammation responses central to the progression of diabetic nephropathy and atherogenic responses." (PMID 32802115, 2020). "Recent evidences indicate that signal transducer and activator of transcription 3 (STAT3) is one of the crucial signaling pathways in the progression of diabetic nephropathy (DN)." (PMID 31699972, 2019). "Acetylation of STAT3 is responsible for its function as a negative regulator of autophagy and it contributes to oxidative changes in diabetic nephropathy." (PMID 26146641, 2015). "Therefore, targeting STAT3 has emerged as a promising strategy in diabetic nephropathy drug discovery." (PMID 40184310, 2025). "Isoquercitrin plays an important role in regulating STAT3 to alleviate diabetic nephropathy." (PMID 40733369, 2025). "In addition, one of the more recently defined Mid-1 ubiquitination targets is non-receptor tyrosine phosphatase PTP1B, whose degradation leads to overactivation of the STAT3 signaling pathway and promotes inflammation and fibrosis in diabetic kidney disease." (PMID 40443734, 2025). "Podocyte hypertrophy observed in diabetic nephropathy (DN) may be related to IL-6 signaling through the activation of Janus kinase 2/signal transducer and activator of transcription 3 signaling pathway (JAK2/STAT3)." (PMID 41150807, 2025). "It has been shown that STAT3 can significantly reduce renal damage in HIV‐related nephropathy, diabetic nephropathy or obstructive nephropathy, while knockout STAT3 gene can significantly reduce fibroblast proliferation and ECM synthesis, ameliorates renal interstitial fibrosis." (PMID 38780509, 2024). "In addition, more recent studies have also reported that Mbnl1 ameliorates diabetic nephropathy via miR-130a-3p/STAT3 axis in response to Metformin." (PMID 39580381, 2024). "Furthermore, miR-20a was indicated to target CXCL6 and modulate JAK/STAT3 signaling, exerting an inhibitory effect on diabetic nephropathy." (PMID 38216907, 2024). "Moreover, PAX8 is involved in the progression of diabetic nephropathy by targeting the miR-17-5p/STAT3 axis and osteoporosis by activating the autophagy of osteoblasts via the miR-1252-5p/GNB1 axis." (PMID 36831395, 2023). "Likewise, CXCL6 is a potential novel therapeutic target and candidate biomarker for JAK/STAT3 signaling in the treatment of diabetic nephropathy." (PMID 36534664, 2022). "Thus, we observed the effect of VHH-0031 on the expression of JAK2/STAT3 expression in diabetic nephropathy." (PMID 34054555, 2021). "Interestingly, the mechanism by which the complement system promotes the development of diabetic kidney disease is the activating of the signal transducer and activator of transcription 3 (STAT3) pathway." (PMID 34831726, 2021). "JAK2 and STAT3, playing key roles in the control of cell proliferation and inflammation, are the most important signal cascades involved in IL-6 transduction in the glomeruli and tubules of diabetic nephropathy." (PMID 34054555, 2021). "STAT3 plays an important role in the pathogenesis of diabetic nephropathy." (PMID 32104542, 2020). "Furthermore, STAT3 is overexpressed in the kidney of diabetic nephropathy patients compared to the ones from normal patients." (PMID 33585566, 2020). "Although our in vitro data using NRK-52E and in vivo data using AAV2/2-shSTAT3 validated the role of renal STAT3 in diabetic nephropathy, the inhibition of STAT3 in other organs by globe treatment with S3I-201 may also contribute to its renal protection." (PMID 31699972, 2019).
diabetic nephropathy (continued). "Knockdown of Stat3 (Stat3SA/-) reduces proteinuria, mesangial expansion, glomerular cell proliferation, and macrophage infiltration in comparison to Stat3SA/+ mice in streptozotocin-induced diabetic nephropathy." (PMID 26872211, 2016). "In addition, the nephroprotection of SIRT1 in diabetic nephropathy is mediated by deacetylation of some transcription factors, including FoxO, RelA/NF-kβ, STAT-3, and PGC-1α/PPARγb, etc., and the higher activity of SIRT1 exerts the renal protective effect for diabetic kidney disease." (PMID 40649025, 2025). "Stat3, an inducible monomeric transcription factor, could be activated by high glucose to induce ER stress, inflammation and oxidative stress in diabetic retinopathy or diabetic nephropathy." (PMID 34645391, 2021). "In vivo and in vitro experiments in diabetic nephropathy models have demonstrated that HDAC9 can induce podocyte apoptosis and renal injury through the JAK2/STAT3 pathway." (PMID 38528189, 2024). "Specifically, SIRT1 mediates the dephosphorylation and deacetylation of p65 NF-κB and STAT3, thereby attenuating inflammation, oxidative stress, and EMT in diabetic kidney disease (DKD)." (PMID 39911234, 2024). "In the glomerular sclerosis and matrix deposition of diabetic nephropathy, JAK2/STAT3 is the most important signal cascade involved in IL-6 transduction." (PMID 34054555, 2021). "Sun’s research found that, in the diabetic nephropathy (DN) model, by activating the JAK/STAT3 signaling pathway, CXCL6 might enhance fibrosis-related variables to hasten the development of DN renal interstitial fibrosis." (PMID 38882664, 2024).
B-cell lymphoma (56 papers, 2009 to 2025). "In contrast, loss of STAT3 in B cell lymphoma cells decreased killing by NK cells in vitro and in vivo." (PMID 39034990, 2024). "The single report of an HIV provirus in a case of AIDS-associated B-cell lymphoma with an HIV provirus in the same part of STAT3 also has implications for HIV-induced malignancy." (PMID 33318172, 2020). "HIV integration into STAT3 has previously been linked, in a case report, to the formation of B cell lymphoma, in which a defective provirus integrated upstream of the first STAT3 coding exon (Top, green triangle)." (PMID 33318172, 2020). "Gain-of-function mutations in STAT6 and STAT3 are frequently observed in B-cell lymphomas." (PMID 40243506, 2025). "However, when we specifically focused on B cell NHL subtypes, there was significant association between STAT-3 protein expression with DLBCL subtypes (p = 0.046)." (PMID 37175040, 2023). "EBV status has been shown to be associated with STAT3 activation in B cell lymphomas." (PMID 32188095, 2020). "STAT3 mutations are rare in B-cell non-Hodgkin lymphoma and other T-cell malignancies." (PMID 31861597, 2019). "Interestingly, a gain-of-function mutation of MYD88 that promotes cell survival via activation of IL-1 receptor-associated kinase 1, nuclear factor (NF)-κB, and JAK/STAT3 signaling is frequently found in cases of a subtype of B-cell lymphoma." (PMID 24662938, 2014). "A rare case of B-cell lymphoma in which a defective HIV-1 was integrated upstream of the first STAT3 coding exon was described in 2007." (PMID 40244051, 2025). "STAT3 inhibition also synergized with inducers of type I IFN, a downstream effector of the cGAS-STING pathway, to effectively inhibit B cell lymphoma growth, possibly by alleviating the suppressive effects of STAT3 on IRF7, IRF9, STAT1, and STAT2 expression." (PMID 40743845, 2025). "HIV provirus integration within this region of STAT3 has previously been described in cases of HIV-associated T cell and B cell lymphomas." (PMID 40627772, 2025). "STAT3 as a target for inhibiting B cell lymphoma cell survival and activating antitumor immune response has been documented." (PMID 39618825, 2024). "This extends to a susceptibility to immune cell cancers, with SNPs in STAT3 and STAT5A being implicated in B cell lymphoma risk and SNPs in STAT3 and STAT6 in Hodgkin lymphoma risk." (PMID 38255152, 2023). "Taken together, these findings suggest that specifically targeting STAT3 siRNA to B cell lymphoma cells can significantly reduce tumor burden and progression." (PMID 37686472, 2023). "NFATc1 can also be activated by the B cell receptor (BCR) and upregulate the IL-10 chemokine to activate the JAK2/STAT3 pathway in B cell lymphoma cells, ultimately inducing PD-L1 expression." (PMID 37138354, 2023). "Comparing different NHL subtypes, aggressive B cell lymphomas (64.2%) were predominantly the STAT-3 protein expression, especially DLBCL subtypes (54.7%)." (PMID 37175040, 2023). "Overall, STAT-3 protein expression was observed in 61 cases (64.2%) of aggressive B cell NHL, with 44 cases (88%) having a strong expression." (PMID 37175040, 2023). "In fact, aberrant STAT-3 signaling plays an important role in immune evasion, and it becomes an oncogenic driver in several types of B-cell lymphoma and, also, in most T-cell lymphomas." (PMID 37175040, 2023). "Among B cell NHL subtypes, we found that there was an association between DLBCL subtypes with STAT-3 protein expression (p = 0.046)." (PMID 37175040, 2023). "Of note, previous studies revealed that HDAC3 regulates STAT3 in B-cell lymphoma by affecting the STAT3 acetylation level and in turn STAT3 nuclear export." (PMID 37019881, 2023).
B-cell lymphoma (continued). "Phosphorylated STAT5, AKT, p70S6K and MAPK were increased in copanlisib-resistant B-cell lymphoma cells, whereas phosphorylated STAT3 and NF-κB were increased in duvelisib-resistant T cell lymphoma cells." (PMID 31601188, 2019). "Constitutive signaling by STAT3 is an oncogenic driver in several types of B-cell lymphoma and most of T-cell lymphomas." (PMID 31861597, 2019). "Aberrant expression and constitutive activation in several types of B-cell lymphoma and in almost all T-cell lymphomas render STAT3 as a promising potential therapeutic target." (PMID 31861597, 2019). "EBV-encoded LMP1 protein activates Stat3 and Akt in EBV-associated malignancies including B cell lymphoma, NPC, and ENKL." (PMID 25887673, 2015). "Inhibition of constitutive STAT3 activity sensitizes resistant B-cell NHL cells to chemotherapeutic cytotoxic drugs, including CHOP, cisplatin, fludarabine, adriamycin, and vinblastine." (PMID 26654227, 2015). "In the same set of large B-cell lymphomas, the ratio of STAT3pSer727 within the total pool of STAT3 also correlated positively (+0.9104) with the ratio of Bcl-2pSer70 in the total pool of Bcl-2." (PMID 26430964, 2015). "Expression analysis of 215 human mature aggressive B-cell lymphomas revealed a positive correlation of IDO1 with STAT3." (PMID 24657910, 2014). "Inactivation of phosphorylation of STAT3 plays an essential role in rituximab-induced anti-proliferative activity in B-cell lymphoma." (PMID 24624997, 2014). "Knockdown of MYD88 expression has significantly inhibited secretion of IL-6 and phosphorylation of STAT3 in B-cell lymphoma cells." (PMID 24662938, 2014). "In summary, we provide evidence that PI3K, NF-κB and STAT3 are interconnected in iMycEμ B cell lymphoma." (PMID 20433747, 2010). "This amplification loop was recently identified in B cells, as B cell-lymphoma with high expression of STAT3 exhibited elevated production of IL-6." (PMID 19284588, 2009). "Its chronic signaling promotes the expansion of B1 cells and plasma cells in B-cell lymphomas, facilitating differentiation through STAT3/6 phosphorylation and contributing to lymphomagenesis, thereby suggesting its involvement in aggressive B-cell malignancies." (PMID 41155287, 2025). "Here, we assessed whether silencing Stat3 with CpG-Stat3 siRNA can significantly enhance the efficacies of CTLA4 antibody therapy in B cell lymphoma by augmenting the immunostimulatory effects." (PMID 39618825, 2024). "In addition, a TLR9 agonist fused to a STAT3 decoy oligodeoxynucleotide (dODN) was also used to inhibit STAT3 in B cell lymphoma." (PMID 37686472, 2023). "Targeting STAT3 represents a promising strategy for the treatment of aggressive cancers displaying a constitutive activation of this pathway, including PEL, which is very aggressive B cell lymphoma KSHV-associated." (PMID 37511362, 2023). "In the present study, we employed this strategy to target STAT3 siRNA into B cell lymphoma." (PMID 37686472, 2023). "In addition, targeting STAT3 with this strategy also leads to decreased cell proliferation and increased apoptosis in two other B cell lymphoma cell lines." (PMID 37686472, 2023). "We have recently reported that a positive feedback loop between STAT3 and HSPs also occurs in primary effusion lymphoma (PEL) cells, a rare B cell lymphoma associated with Kaposi sarcoma herpesvirus (KSHV) and, in most of the cases, also with Epstein–Barr virus (EBV)." (PMID 37511362, 2023). "there was investigation reported that pharmacologic or genetic disruption of STAT3 could enhanced the immunogenicity of cancer cells and further resulted in functional promotion of T cells in B-cell lymphomas." (PMID 31511071, 2019). "For B cell lymphoma, IL-6 and IL-10 feedback mediate STAT3 constitutive activation." (PMID 31552035, 2019).
B-cell lymphoma (continued). "Thus, while S1PR1 is expressed at low levels in CLL lymph nodes as compared with normal B cells, increased expression of S1PR1 correlates with signal transducer and activator of transcription 3 (STAT3) activation and survival in B-cell lymphoma." (PMID 27800303, 2016). "Overexpressed IL-23 enhances antitumor activity in SU-DHL-4 human B cell lymphoma cell inoculated xenograft model, however, it is also regulated that endogenous IL-23 promotes pro-tumor activity through STAT3 activation by inducing inflammatory responses including IL-17 production." (PMID 26993600, 2016). "Notably, a strong correlation between the expression and/or phosphorylation of STAT3 and Bcl-2 was observed in primary tissues derived from patients with different sub-sets of B cell lymphoma." (PMID 26430964, 2015). "In addition, inhibition of JAK2 does not only block the activation of STAT3 but also the activity of STAT1 in B-cell lymphoma." (PMID 26654227, 2015). "Thus, the relative levels of Myc versus LMP1 in B cell lymphomas likely determine whether the activated forms of STAT3 and Src are expressed." (PMID 38620028, 2024). "They demonstrate that combination of the TLR9 agonist (CpG) with the STAT3 decoy inhibitor into a single oligodeoxynucleotide conjugate generates two-pronged therapeutic effect by direct and T cell-mediated antitumor effects against B cell lymphoma cells in vivo." (PMID 29433938, 2018). "For our experiments, we selected the commonly used mouse A20 B cell lymphoma model, which exhibits TLR9 expression and constitutive Stat3 activation." (PMID 39618825, 2024). "In the present study, we demonstrate that blocking STAT3 through locally delivered CpG-Stat3 siRNA enhances the efficacies of the systemic PD-1 and CTLA4 blockade against mouse A20 B cell lymphoma." (PMID 39618825, 2024). "We found that B-cell lymphoma (BCL) patients have dysregulated expression of intracellular and extracellular HSPs, immune checkpoints PD-1, CTLA-4, and STAT3 in CD3/CD28-activated T cells." (PMID 36359267, 2022). "In the perspective of B-cell lymphoma we propose JAK2 to be inhibited by ibrutinib and regulating the subsequent phosphorylation of STAT3 and 6 leading to decreased transcription of M2 macrophage phenotype genes." (PMID 32824276, 2020). "STAT3 was found to be constitutively active, typically phosphorylation at Y705, in EBV-positive nasopharyngeal cell carcinoma, EBV-positive B cell lymphomas, and KSHV tumors, supporting the role of STAT3 activation in gammaherpesvirus-related cancers." (PMID 32735617, 2020). "STAT3 is phosphorylated in 20–40% of mantle cell lymphoma (MCL), an aggressive, rare form of B-cell non-Hodgkin lymphoma." (PMID 31861597, 2019). "More recently it was shown that ZIP10 is transcriptionally regulated by signal transducer and activator of transcription 3 (STAT3) and STAT5, and suppresses apoptosis in human B-cell lymphoma." (PMID 27274087, 2016). "Together, these data implicate crosstalk among NF-κB, STAT3 and PI3K in the development of iMycEμ B-cell lymphomas." (PMID 20433747, 2010). "Silencing Stat3 through locally delivered CpG-Stat3 siRNA significantly enhanced the antitumor efficacies of systemic administration of PD-1- and CTLA4-specific antibodies in mice bearing the A20 B cell lymphoma arresting tumor growth." (PMID 39618825, 2024). "Signaling crosstalk of NF-κB, STAT3 and PI3K may play an important role in Myc-induced B-cell lymphoma in mice." (PMID 20433747, 2010). "More direct STAT3 inhibitors are in development, such as the dual-function molecule CpG-STAT3dODN, which consists of a TLR9 (Toll like receptor) agonist (CpG7909) and a STAT3 inhibitor, high-affinity decoy oligodeoxynucleotide for B-cell lymphoma immunotherapy." (PMID 30217007, 2018).